GAST (gastrin)
Diseases named in the same sentence as GAST in open-access papers (continued):
Sharing a sentence is not in itself a finding about the gene and the disease.
cancer (continued). "Taken together it appears that expression of CCK2R may provide a mechanism that allows gastrin to determine the position of myofibroblasts as they progress through the cell cycle which might be particularly relevant during wound healing or in cancer." (PMID 29038353, 2017). "We also tested whether knockdown of CacyBP expression with siRNA affects the ability of gastrin to stimulate proliferation of cancer cells." (PMID 28196083, 2017). "Together with previous findings, the results raise the prospect that gastrin controls the position of dividing myofibroblasts which may be relevant in wound healing and cancer progression in the gastrointestinal tract." (PMID 29038353, 2017). "Gastrin has been thought to stimulate the growth of other cancers." (PMID 25698559, 2015). "Although not all studies agree on the role of gastrin in cancer development, the possible risk of cancer due to gastrin stimulation needs to be acknowledged." (PMID 25698559, 2015). "Receptors for peptides secreted by neuroendocrine cells, such as secretin, gastrin, bombesin, cholecystokinin, and vasoactive intestinal peptide, have been identified in many cancer types, including cancers of lung, ovarian, thyroid, brain, genitourinary and gastrointestinal tract." (PMID 24392036, 2013). "In addition to regulating gastric acid secretion, mature gastrin (G-17) and its unprocessed intermediate forms progastrin and glycine extended gastrin (Gly-G) can regulate growth in a variety of cancer cells." (PMID 20637111, 2010). "Aberrant HGF/c-Met signalling has been well documented in a variety of human cancers, and our results strengthen the view that also the gastrin signalling pathway could be involved in oncogenesis." (PMID 15846300, 2005). "Serum gastrin may serve as a valuable marker for post-ESD cancer surveillance in GCAE patients." (PMID 39518740, 2024). "Thus, when carcinomas are developed from extraantral cells that normally express the gastrin gene at a low level, carcinomas may also express gastrin." (PMID 34209478, 2021). "Moreover, since we already have an efficient and safe gastrin antagonist, netazepide, this compound may be used to prevent cancer development." (PMID 32796591, 2020). "Therefore, it can be speculated that by suppressing gastrin secretion, curcumin disrupts a cascade of cancer‐related events to impede the development of cancer." (PMID 28781948, 2017). "Some of the metal ion-gastrin complexes may be useful for cancer diagnosis and therapy." (PMID 26457677, 2015). "Several studies showed the strong relationships between GAST gene activation, WNT pathway activation, and hPG80 expression in adenoma and cancer cells." (PMID 40598473, 2025). "Elevated gastrin levels may be a potential risk factor for cancer development in Hp-negative AIG." (PMID 41210850, 2025). "Many of the diffuse types express neuroendocrine and, more specifically, ECL cell markers, suggesting that these cancers develop from ECL cells, which are the target cells of gastrin." (PMID 37941554, 2023). "Expression and function profiles of gastrin, CCK, and their receptors in human cancer cell lines and tissues." (PMID 32210918, 2020). "In silico analysis of common genes revealed possible genetic pathways in common between cancer and suicide, like the cadherin signaling pathway and the CCKR (gastrin/cholecystokinin receptor) signaling map." (PMID 31797972, 2019). "Cancer cells produce and secrete the neuropeptides CCK/gastrin, GRP and NMB, bradykinin, and vasopressin." (PMID 29262666, 2017). "Further, inactivation of GSK-3β can upregulate β-catenin during gastrin and TNF-α induced EMT of cancer cells." (PMID 27058759, 2016). "In cancer, progastrin does not maturate in gastrin and becomes a circulating and detectable protein (hPG80)." (PMID 38672239, 2024).
cancer (continued). "Cell survival and proliferation, proinflammatory cytokine expression and TGR5/STAT3/KLF5 axis activity were measured in normal human gastric cells, cancer cells, and organoid lines derived from C57BL/6, FVB/N and insulin-gastrin (INS-GAS) mice treated with DCA." (PMID 36067404, 2022). "Polyclonal Antibody Stimulator (PAS) is a therapeutic immunogen cancer vaccine comprised of a nine amino acid epitope derived from the amino-terminal sequence of gastrin-17 that is conjugated to diphtheria toxoid." (PMID 34926305, 2021). "In addition to the acute digestive effects, both gastrin and CCK have been suggested to exert potent proliferative and anti-apoptotic effects by contributing to pathogenesis and progression of cancer." (PMID 32210918, 2020). "Furthermore, we did not include specific postgastric cancer surgery gastrointestinal function indicators, such as gastrin." (PMID 39165684, 2024). "When curative surgery is not possible, a gastrin antagonist may be of value, at least in those patients with cancers expressing the gastrin receptor." (PMID 37941554, 2023). "Here, we found the effect of gastrin on the expression levels of COX17, COX5B, and ATP5J proteins that are involved in the mitochondrial respiratory chain, which may reveal one of the important mechanisms of gastrin as a cancer promoting factor." (PMID 33937399, 2021). "However, it should be noted that the CCK2R- and CCK1R-mediated signal transduction varies in the context of cell types, suggesting that cautions should be taken in future investigations attempting to target the gastrin and CCK system for the treatment of certain types of cancer." (PMID 32210918, 2020). "Expression of genes that play an anti-apoptotic role in cancer has been shown to be maintained via use of an IRES, and since such a role has also been ascribed to gastrin in GI cancer cells, we investigated whether the gastrin IRES was active during apoptosis induced by the genotoxic agent, MMC." (PMID 18392051, 2008). "Furthermore, if the CCK-BR-targeted NP can also deliver gastrin siRNA or other payloads to the PanIN lesions such as siRNA for mutant KRAS, these NPs would have the potential not only to identify but also to also treat these PanIN lesions to decrease proliferation and halt the progression to cancer." (PMID 34944412, 2021). "Although a higher cut-off value for gastrin was required in PPI users compared to non-PPI users, the predictive ability remained low, indicating that PPI-induced elevations in gastrin levels do not contribute to cancer prediction." (PMID 39518740, 2024).
infection (21 papers, 2007 to 2026). The state of being infected such as from the introduction of a foreign agent such as serum, vaccine, antigenic substance or organism. "A reduced antral expression of H+/K+ ATPase was seen in the stomach after infection with 3 highly colonizing strains and 2 highly colonizing strains caused an increased gastrin expression in the fundus." (PMID 23895283, 2013). "As to the serum gastrin level, a significant interaction was found between infection and acid suppressants." (PMID 35935877, 2022). "The presence of parasites in the lumen, either immature adults after L3 infection or transplanted mature adult worms, increased abomasal pH and serum gastrin and pepsinogen concentrations." (PMID 29073245, 2017). "pylori and measured gastrin mRNA levels by quantitative reverse transcription PCR (qRT-PCR) at 2.5 and 5 h post-infection." (PMID 29379775, 2017). "G27 significantly induced gastrin mRNA expression by as much as 1.7-fold as compared to control cells at 4 h post-infection and furthermore induced gastrin promoter activity by as much as 4-fold." (PMID 29379775, 2017). "More importantly, WT infection of G240-Luc cells carrying cleavable HB-EGF resulted in a significantly higher level of gastrin promoter activity than seen with the G240-Luc cells carrying the UcHB-EGF." (PMID 29379775, 2017). "In H. pylori-infected gerbils, gastrin levels started to increase only after 16 weeks of infection and mainly in antral tissue." (PMID 23895283, 2013). "Further studies, measuring the levels of IL-1β, gastrin, histamine and somatostatin after long term experimental infection, are necessary to obtain additional insights into the influence of H. heilmannii s.s. on gastric homeostasis." (PMID 23895283, 2013). "INS-GAS mice with chronic gastric Helicobacter infection have significantly raised circulating amidated gastrin concentrations compared to uninfected INS-GAS controls at 9 months post infection." (PMID 23185574, 2012). "The fact that human gastrin levels are elevated during infection with H. pylori and return to basal levels after eradication of the bacterium confirms that H. pylori is normally exposed to this human hormone." (PMID 22399982, 2009). "This study investigated sonic hedgehog (Shh) signalling in gastric metaplasia in the insulin-gastrin (InsGas) hypergastrinaemic mouse +/− Helicobacter felis (H. felis) infection." (PMID 17505514, 2007). "According to other studies, infection by H. pylori may increase the release of gastrin, which acts on intestinal epithelial cells and stimulates the production of cox-2, a well-known player in the occurrence, development, invasion, and metastasis of CAC." (PMID 32104172, 2020). "As expected, infection with G27 significantly induced gastrin promoter activity in the G240-Luc cells carrying pcDNA3, and G27 infection of the G240-Luc cells carrying either pUCHB-EGF or pHB-EGF resulted in significantly higher levels of induction than in the G240-Luc cells carrying pcDNA3." (PMID 29379775, 2017). "We assume that a strong interaction of an early induced atrophy of the parietal cells together with a significantly increased stimulation of the G-cells in the antrum to release gastrin after 32 weeks of WT-infection, is responsible for severe precancerous transformations of the gastric cells." (PMID 19270747, 2009). "A further increase of gastrin mRNA levels by one log stage was obtained at 64 weeks of infection." (PMID 19270747, 2009). "Abnormal gastrin secretion resulting from infection may chronically activate the PI3K/Akt pathway, promoting β-cell apoptosis and impairing islet function, while also disrupting the gut–islet axis and attenuating the glycemic regulatory role of glucagon-like peptide-1 (GLP-1)." (PMID 40880764, 2025).
infection (continued). "The data clearly show that the H. pylori WT-infection induces a relatively early increase of inflammatory markers (between 4 and 8 weeks) but a relatively late (at 16 and 32 weeks) increase in physiological parameters such as the gastric pH and the plasma gastrin level." (PMID 19270747, 2009). "Further investigation into the cellular targets of gastrin signaling is needed to inform the potential effects of hypergastrinemia secondary to PPI use and infection by H. pylori." (PMID 35330921, 2022). "Infection of the gastric epithelial cells with H. pylori increased HB-EGF mRNA expression at 1 h and subsequently induced gastrin mRNA expression at 4 h." (PMID 29379775, 2017). "For G27 WT infection, pretreatment of cells with AG1478 significantly reduced both H. pylori-induced gastrin mRNA expression and gastrin promoter activation." (PMID 29379775, 2017). "The expression of gastrin was highly up-regulated in the fundus of gerbils infected with ASB2 and ASB6 at 9 weeks post-infection." (PMID 23895283, 2013). "In our study, the change of PG level by responding to PPI/PCAB administration is larger in previous infection cases than in current infection cases, whereas the change of gastrin level by PPI/PCAB administration was not different." (PMID 35126509, 2022). "Of note, gastrin promoter activity was not induced significantly at 3 h post-infection (data not shown)." (PMID 29379775, 2017). "Furthermore, a study found that (insulin–gastrin) INS-GAS mice coinfected with H. pylori and Streptococcus salivarius developed more severe gastric inflammation than did H. pylori only at 5 months post-infection." (PMID 31781514, 2019). "Since activation of the EGF receptor is important for H. pylori-induced gastrin promoter activation, the absolute levels of mRNA expression were next determined for the EGF family members (HB-EGF, AR, EGF, TGF-α, BTC, epigen, and epiregulin) using qRT-PCR at 1, 2.5, and 5 h post-infection." (PMID 29379775, 2017). "However, those mRNA data are not directly correlating with the pH values and plasma gastrin levels observed after 16 weeks of infection." (PMID 19270747, 2009).
adenocarcinoma (13 papers, 2002 to 2024). A common cancer characterized by the presence of malignant glandular cells. "Based on previous researches, HPI probably occurs in childhood or adolescence and is associated with of increased gastrin release, which could promote the development of potential adenocarcinoma." (PMID 30665367, 2019). "We and others have shown that gastrin regulates several important cellular processes in the gastric epithelium and in adenocarcinoma cells including proliferation, anti-apoptosis, migration and invasion." (PMID 25384047, 2014). "We used time series microarray data of AR42J adenocarcinoma cells treated with gastrin combined with static TF-TG relationships integrated from different sources, and we reconstructed the dynamic activities of TFs using network component analysis (NCA)." (PMID 24416123, 2014). "Microarray mRNA profiling of gastrin-treated pancreas derived adenocarcinoma cells (AR42J) demonstrated that gastrin transiently activates Sik1 gene expression (Accession number: GSE32869)." (PMID 25384047, 2014). "The aim of this study was to examine the role of SIK1 in gastrin responsive adenocarcinoma cell lines AR42J, AGS-GR and MKN45." (PMID 25384047, 2014). "Genome-wide microarray time series analysis was also used to identify genes that are affected by the duration of gastrin treatment in adenocarcinoma cells." (PMID 24086717, 2013). "We have used genome-wide microarray time series analysis and molecular studies to identify genes that are affected by the duration of gastrin treatment in adenocarcinoma cells." (PMID 23805861, 2013). "We have therefore conducted the present study to examine how adenocarcinoma cells respond to transient versus sustained gastrin signalling and to identify characteristic differences between downstream biological responses." (PMID 23805861, 2013). "In this study we demonstrate that gastrin induces Nuclear Receptor 4A2 (NR4A2) expression in the adenocarcinoma cell lines AR42J and AGS-GR, which both possess the gastrin/CCK2 receptor." (PMID 24086717, 2013). "Gastrin induces expression of clusterin in adenocarcinoma cells." (PMID 28902909, 2017). "The major contribution of this study is that we by extensive time series gene expression analysis and molecular studies characterize the distinct effects of duration of gastrin treatment on intracellular signalling events and gene expression in adenocarcinoma cells." (PMID 23805861, 2013). "Therefore, increased gastrin gene expression could be partly responsible for the down-regulation in CCK-2 receptor gene expression seen in the adenocarcinomas." (PMID 12189558, 2002). "We show that gastrin, known to signal through the Gq/G11-coupled CCK2 receptor, induces SIK1 expression in adenocarcinoma cells, and that transcriptional activation of SIK1 is negatively regulated by the Inducible cAMP early repressor (ICER)." (PMID 25384047, 2014). "In the present study we show that gastrin-mediated signalling, known to involve the Gq/G11-coupled CCK2 receptor and signalling pathways like PI3K-PKB/Akt, PKC and MEK-ERK1/2, induces transient SIK1 expression in adenocarcinoma cells." (PMID 25384047, 2014).
GI tumours (7 papers, 1991 to 2021). "This receptor has been shown to be coexpressed with gastrin in several GI tumour cell lines and in human gastric carcinoids, indicating the existence of an autocrine gastrin growth-stimulatory loop." (PMID 15846300, 2005). "Gastrin is involved in the establishment of a range of GI tumours." (PMID 17262081, 2007). "Owing to the complexity of the products arising from the gastrin gene and the low levels of gastrin protein produced by GI tumour cells, the effect of siRNA transfection on gastrin protein expression was initially analysed using HCT116 cells transfected with a GFP-tagged gastrin gene." (PMID 17262081, 2007). "However, the cellular and molecular mechanisms governing any possible relationship between gastrin and COX during GI tumour growth have not been elucidated." (PMID 12189559, 2002).
colon polyps (4 papers, 2002 to 2023). "The potential mechanism of the significant association between colon polyps and serologic H. pylori positivity has been attributed to the remote trophic effect of the elevated gastrin level on the colonic mucosa." (PMID 18702825, 2008).
gastrointestinal disease (4 papers, 2020 to 2024). A disease that occurs in the gastrointestinal system, excluding the hepatobiliary system. "During deeper sleep stages, the human body increases defensive factors (gastric bicarbonate efflux, gastric mucosal blood flow, and melatonin secretion) and decreases aggressive mediators (gastrin secretion) against gastrointestinal diseases." (PMID 38992594, 2024). "Gastrin plays important role in stimulating the initiation and development of many gastrointestinal diseases through interacting with the cholecystokinin 2 receptor (CCK2R)." (PMID 36756145, 2022).
Gastrointestinal disorders (2 papers, 2024). "In conclusion, the increased levels of gastrin observed in this population underscore the importance of conducting a comprehensive clinical assessment to identify potential gastrointestinal disorders, particularly in consideration of the usage of omeprazole as a preventive treatment." (PMID 38672316, 2024). "The identification of increased gastrin levels within this population emphasizes the critical need for a comprehensive clinical evaluation of potential related gastrointestinal disorders, with special attention given to the use of omeprazole as a chronic preventive treatment in dogs." (PMID 38672316, 2024).
kidney disease (2 papers, 2014 to 2023). "In addition, in both studies, at least 70% of cats with CKD had moderate to severe kidney disease, limiting assessment of gastrin concentrations in cats with earlier stage CKD." (PMID 37874019, 2023).
psychiatric disorder (2 papers, 2024 to 2025). A disorder characterized by behavioral and/or psychological abnormalities, often accompanied by physical symptoms. "The results demonstrated that tcVNS can reduce gastrin levels and modulate hormonal and autonomic responses to stress, thereby treating psychiatric disorders." (PMID 39221007, 2024).
cardiovascular disease (1 paper, 2022). "Since then, others have associated gastrin concentrations in plasma with cardiovascular disease, but it was not pursued from which organ the gastrin originated." (PMID 36101352, 2022).
endocrine neoplasm (1 paper, 2020). "In addition, co-secretion of other ectopic hormones (i.e., calcitonin, gastrin and 5-HT) from an endocrine neoplasm may suggest a de-differentiation usually related to a more aggressive behaviour." (PMID 32384679, 2020).
respiratory diseases (1 paper, 2025). "Based on previous research, this phenomenon may be explained by ACS promoting gastrointestinal maturity (e.g., increased gastrin secretion), improving feeding tolerance, and indirectly supporting growth by reducing severe respiratory diseases." (PMID 41113556, 2025).